TLX1NB (TLX1 neighbor)
Synonyms: TDI; TD1; APT-B7
Gene: Long non-coding RNA gene on chromosome 10 (101,089,321 to 101,141,438, reverse strand). Ensembl gene ENSG00000236311.
Diseases named in the same sentence as TLX1NB in open-access papers:
TLX1NB is named in the same sentence as 10 diseases in open-access papers, as found by Europe PMC text mining. Sharing a sentence is not in itself a finding about the gene and the disease. The quoted sentences say what the papers report.
CNS cancer (1 paper, 2020). "Previous studies have demonstrated that TLX1NB can be a prognostic lncRNA biomarker in lung adenocarcinoma; however, there are no other studies revealing the role of TLX1NB in CNS cancer." (PMID 33102572, 2020).
colon cancer (1 paper, 2022). "Firstly, TLX1NB was up-regulated in colon cancer tissues and increased TLX1NB expression was significantly associated with advanced N stages." (PMID 35502613, 2022). "HCT116 cells were used to generate a colon cancer cell line stably overexpressing TLX1NB via transduction of the LV-oeTLX1NB vector, leading to pronounced TLX1NB upregulation (P < 0.001)." (PMID 35502613, 2022). "To further investigate the mechanisms governing TLX1NB-mediated regulation of colon cancer cell invasion and metastasis, we detected the expression levels of STAT5A and p-STAT5A following TLX1NB knockdown or overexpression." (PMID 35502613, 2022). "We initially explored the clinical relevance of TLX1NB in colon cancer through a series of bioinformatic analyses." (PMID 35502613, 2022). "In our study, we investigated the clinical significance of TLX1NB in colon cancer through bioinformatics analysis and explored its role in migration, invasion and metastasis of colon cancer cell with a series of experiments." (PMID 35502613, 2022). "We performed a series of in vitro and in vivo experiments to investigate the role and mechanism of TLX1NB in colon cancer invasion and metastasis." (PMID 35502613, 2022). "Next, we assessed the impact of TLX1NB expression on the migratory and invasive activity of colon cancer cells using a transwell assay system." (PMID 35502613, 2022). "In addition, we found that TLX1NB promoted the invasion and metastasis of colon cancer cells by enhancing STAT5A phosphorylation." (PMID 35502613, 2022). "Based on the results of previous studies, we hypothesized that TLX1NB promoted colon cancer invasion and metastasis by enhancing STAT5A phosphorylation." (PMID 35502613, 2022). "We investigated the role of TLX1NB in colon cancer invasion and metastasis." (PMID 35502613, 2022). "In this study, we investigated the role of TLX1NB in colon cancer invasion and metastasis through a series of wet and dry experiments and reported that TLX1NB enhanced STAT5A phosphorylation to promote colon cancer cell invasion, migration, and metastasis for the first time." (PMID 35502613, 2022). "First, we scanned TCGA and identified TLX1NB as lncRNA that is upregulated in colon cancer." (PMID 35502613, 2022). "Thus, TLX1NB may drive colon cancer cell migration and invasion, at least in part by promoting STAT5A phosphorylation." (PMID 35502613, 2022). "However, the specific mechanistic role of TLX1NB in colon cancer remains unclear." (PMID 35502613, 2022).
colorectal cancer (1 paper, 2022). A primary or metastatic malignant neoplasm that affects the colon or rectum. "The lncRNA T cell leukemia homeobox 1 neighbor (TLX1NB) is encoded in the human 10q24.31 chromosomal region and was reported to be upregulated in colorectal cancer (CRC) tissues." (PMID 35502613, 2022). "The long noncoding RNA (lncRNA) T cell leukemia homeobox 1 neighbor (TLX1NB) is up-regulated in colorectal cancer (CRC)." (PMID 35502613, 2022).
cancer (2 papers, 2020 to 2022). A tumor composed of atypical neoplastic, often pleomorphic cells that invade other tissues. "Using the American Joint Committee on Cancer staging system, we found that TLX1NB was expressed at higher levels in N2 stage COAD samples than in N0 (P < 0.05) or N1 (P < 0.05) stage samples." (PMID 35502613, 2022).
tumor (1 paper, 2020). "TLX1NB probably affects LGG through the tumor activating pathway and could be a meaningful biomarker for LGG." (PMID 33102572, 2020).
TLX1NB also shares sentences with these, for which no sentence is quoted: glioma (1 paper); Infertility (1); lung adenocarcinoma (1); skeletal dysplasia (1); tetanus (1).